CD68 (CD68 molecule)
Diseases named in the same sentence as CD68 in open-access papers (continued):
Sharing a sentence is not in itself a finding about the gene and the disease.
tumor (continued). "We also analyzed the correlation between the expression of CCL2 in tumor cells and macrophage infiltration in GSE125449 cohort and found that there was a positive correlation between the expression of CCL2 in KRT18 + tumor cells and CD68 + macrophages infiltration." (PMID 38970074, 2024). "Our mechanistic study revealed that TBC1D1-mediated inhibition of CTL function could be attributed to the upregulation of various immune checkpoint molecules, including ARG1, CD68, PDCD1, CD274, TGFB1, and CTLA4, collectively impeding the anti-tumor immune response." (PMID 38529286, 2024). "Here, even tumor spots with high CD68 scores did not reveal specific detection of Rep." (PMID 36811271, 2024). "Additionally, the tumor sample contained various other cell types, including epithelial cells (EPCAM+), pStr (MKI67+) CD4+T cells (CD4+), CD8+ T cells (CD8A+), macrophages (CD68+), and regulatory T cells (FOXP3+), which were further validated by our single-cell data." (PMID 39676856, 2024). "To put the TME-Analyzer to the test, we imaged tumor border and center regions with Multiplexed immunofluorescence (MxIF) in whole slide sections of 63 primary TNBC patients and assessed the presence of CD3, CD8, CD20, CD56, CD68 and pan-Cytokeratin (CK)-positive cells." (PMID 40604303, 2024). "Interestingly, we found that TAM Macro‐2 was preferentially enriched in the interstitial region but also infiltrated the tumor region, indicating that tumor cells may hijack CD68+CD86− to restrain the immune response and promote tumor growth." (PMID 38483933, 2024). "However, CD68 is also expressed in non-myeloid cells such as lymphoid cells, fibroblasts and tumor cells." (PMID 38898200, 2024). "Analysis in CRC also shows a significantly higher frequency of CD4 + Foxp3 + Treg cells and CD68 + CD163 + M2 macrophages in intratumoral TLS compared to peritumoral TLS, suggesting a potential correlation between peri-tumor TLS and the immunosuppressive environment within the tumor." (PMID 39068459, 2024). "Additionally, immune checkpoint molecules (e.g., CCR4, CD27, CD274, CD68, CTLA4, PDCD1, and PDCD1LG2) were significantly upregulated in the AERShigh group (all p < 0.01), suggesting potential impairment of the anti-tumor immune response." (PMID 39464883, 2024). "Aiming at a particular identification of the predominant cell types and the accordingly conveyed tumor-modulating effects, additional staining analyses of the present EOC patient cohort defined the subset of ACTBL2-positive TILs as CD44-expressing cytotoxic T-cells (CD8 +) and macrophages (CD68 +)." (PMID 38114558, 2023). "Hence, CD68+ and CD163+ TAM might collaborate in assisting tumoral cells to leave the primary tumor and invade lymph nodes due to the increasing vascularization and the induction of tumoral cell spreading." (PMID 37465638, 2023). "Our results verified peri-tumoral infiltration level of CD68+ macrophages compared to paired tumor samples of no BTS group and HL group, indicating macrophage-based therapeutics like CD47 blockade that promotes macrophage phagocytosis 40 being possibly feasible." (PMID 37215452, 2023). "Tumour-immune phenotype distribution differed depending on the immune cell subset, however, hot tumour-immune phenotypes (high density of immune cells in tumour areas) were frequently found for CD8 + T-cells (33%), especially perforin + lymphocytes (52.2%), and CD68 + macrophages (37.6%)." (PMID 36726072, 2023). "Next, we compared the proportion of CD4, CD8, CD19, CD68 and Foxp3 positive cells in lymphocytes of patients with high and low expression of ICOSLGTCs, as well as the proportion of CD4, CD8 positive cells and Fopx3+ cells, and divided them into invasive Frontier and tumor center for analysis." (PMID 37842091, 2023).
tumor (continued). "The biomarker analysis showed that PD-L1 combined positive score (CPS), tumor CD68 and CD4 protein levels (representing cell surface protein markers for TAMs), and tumor-infiltrating CD4 T cells could be potential predictive markers for cabozantinib plus durvalumab activity in this setting." (PMID 37958363, 2023). "In addition, GAS6-CAR-T cells could significantly reduce AXL and CK19 double-positive tumor cells, as well as AXL and CD68 double-positive macrophages." (PMID 37475048, 2023). "In total, five populations were designated tumour clusters, which had various features: (TumourC0) CD74 and APOD; (TumourC1) IF16, JUN and HSPA1A; (TumourC2) S100B and SCRG1; (TumourC3) NEAT1 and MALAT1; and (TumourC4) WFDC2 and RNASE1 (HLA‐DRA, CD68, CD3D, CD3E)." (PMID 37784253, 2023). "However, adropin in tumor stroma cells was positively correlated with local CD68 and ARG1 without any effects on iNOS." (PMID 37904094, 2023). "Interestingly, the accumulation of CD68+CD206+ M2-like TAMs appears to be influenced at least in part by the presence of soluble factors (e.g., folate receptor β) produced by tumor cells in the TME that favor the polarization and recruitment of M2-like macrophages." (PMID 37958292, 2023). "In this exploratory study we identified that CD68+CD163+CD206neg M2 macrophages were the predominant macrophage subtype in CLM, predominantly located in the tumor periphery with relatively higher density than the tumor center supported by the cellular spatial analysis." (PMID 37637998, 2023). "Most notably, the tumor was found to be negative for Brachyury, CD68, SRY-box transcription factor 10 (SOX10), HMB45, glial fibrillary acidic protein, oligodendrocyte transcription factor 2, anaplastic lymphoma kinase, desmin, CD117, synaptophysin, and neurofilament." (PMID 37598295, 2023). "In tumor stroma, CD68-expressing cells were not positive for VPAC1 staining." (PMID 36650220, 2023). "Moreover, mIHC staining confirmed different expression levels of CD68+ &APOE+ macrophages, FOXP3+ &TNFRSF4+ Tregs, VEGFA, and TGFβ signaling between the tumor microenvironment of the de novo mild OLK and the OLK with moderate to severe dysplasia in clinical study." (PMID 36914617, 2023). "Interestingly, immunostaining with the anti-CD68 antibody revealed that the infiltration of TAMs followed the microbeam paths in mouse LLC1 carcinomas at 7 and 16 days post-irradiation, predominantly in the tumour periphery." (PMID 35453485, 2022). "Interestingly, density of CD8+ and GZMB+ cells were of consistent prognostic value regardless of their tumour proximity, whereas CD68+ cell density had the greatest prognostic effect in the TP25μm zone and decreased in locations more distant to the tumour." (PMID 36114487, 2022). "In addition, heterotopic tumors from CreERT2 mice showed diminished inflammation demonstrated by reduced presence of total leukocytes (CD45+ area), TAMs (CD68+ area), neutrophils (MPO+ cells), tumor-infiltrating lymphocytes, TILs (FOXP3+), as well as T regulatory cells, Tregs (FOXP3+CD4+ cells)." (PMID 35688943, 2022). "Tumor-supporting activity mediated by macrophage SRs includes regulation of tumor invasion, proliferation and migration (for CD204, CD206, CXCL16, Stabilin-1, and RAGE), as well as M2-like TAM polarization (for CD36, LOX-1, CXCL16, CD 163, and RAGE) and tumor angiogenesis (for CD68, Dectin-1, RAGE)." (PMID 36686729, 2022). "Furthermore, the absolute number of CD8- and CD68-positive cells per mm2 in BCC was significantly lower compared to cSCC (p ≤ 0.001) in the tumor epithelium, the tumor stroma, the entire tumor (epithelium and stroma), and the tumor invasion front." (PMID 35463364, 2022). "Substantial numbers of VEGF-C+ CD68+ CD163+ TAMs were distributed in the lesional skin of Merkel cell carcinoma, and expression of CD200 in tumor cells induces immunosuppressive CD163+ CD200R+ M2 TAMs and Foxp3+ Tregs to maintain the immunosuppressive tumor microenvironment." (PMID 35409404, 2022).
tumor (continued). "Thus, density numbers of infiltrating CD8+, CD4+, and FOXP3+ T-cell lymphocytes, CD20+ T-cell lymphocytes, and CD68+ and CD163+ macrophages were separately evaluated in both the tumor nests and surrounding stroma, and the mean numbers were correlated with the mean values for NLR, PLR, SII and LMR." (PMID 35958590, 2022). "In addition, non-tumor PD-L1 expression was shown in CD68+ tumor-associated macrophages in all eight patients, whereas in only one responder with MSI-H, less than 5% of PD-L1 was observed on tumor cells." (PMID 35326618, 2022). "Strikingly, among the biomarkers examined, CD19, followed by CD68 and CD8, were the most co-stained markers with THBS2, suggesting that THBS2 mainly impacts B cells, macrophages and CD8+ T cells within TIME, thus potentially modulating tumor immunity via interacting with these immune cells." (PMID 35547750, 2022). "The presence of cells expressing the CD206 receptor but not CD68 (pan-macrophage) may indicate a different cell type, most likely tumour-infiltrating dendritic cells." (PMID 35453485, 2022). "In addition, patients in S3 had high levels of the macrophage marker gene CD68 and EMT marker genes such as MMP2 and MMP9, indicating that these cells in the tumor microenvironment may play important roles in tumor progression." (PMID 35124891, 2022). "CD68 positivity was confined to the tumor stroma and not epithelial nests." (PMID 35964339, 2022). "Furthermore, Gal-9 is mainly expressed in CD68+CD163+ KCs, indicating it may promote tumor progression through the induction of immunosuppressive microenvironment." (PMID 35202002, 2022). "The expression of multiple immune cells (CD8, Foxp3, CD68, CD163, CD20, CD11c, CD66b, CD56, PD-L1, INF-γ, Ki67 and VEGFR-2) in the tumor center (TC), tumor invasive front (< 150 μm from the tumor center, TF) and peritumoral region (≥ 150 μm from the tumor center, PT) was evaluated via comparison." (PMID 36195882, 2022). "A tumor biopsy was performed, and the histological findings of the tumor lesion showed a proliferation of tumor cells that were positive for myeloperoxidase and CD68 and negative for CD4 and CD123." (PMID 33976945, 2021). "Given recent reports that the balance between effector and suppressor immune subsets may offer more useful prognostic information, we evaluated the correlation between ratios of CD8+/FOXP3+, CD3+/FOXP3+, CD4+/FOXP3+, and CD68+/CD163+ and survival in tumor samples at diagnosis and after NACT." (PMID 32852603, 2021). "In addition, EBF1-expressing cells did not express monocyte/macrophage markers CD68, CD163 or Tie-2, recognized markers of tumor-associated macrophages with pro-angiogenic properties." (PMID 34272603, 2021). "In our multivariate analysis, the presence of CD68 + CLS-B (without quantitation) was associated with worse OS (but not DFS) when adjusted for patient and tumour characteristics such as age, BMI, tumour grade and tumour stage." (PMID 34294716, 2021). "In leukemia, prostate, lung, pancreatic, colon, and gastric cancers, CXCL13 exhibits pro-cancer effects by recruiting B cells, CD68+ macrophages, regulatory B cells (Bregs), Treg, and CD40+ MDSCs, shaping an immune-suppressive TME to trigger tumorigenesis and tumor progression." (PMID 34947813, 2021). "The initial tumor site had no evident tumor cells while having multiple CD68+ positive cells." (PMID 34940358, 2021). "However, this should not be misleading, as it is not a fibrohistocytic-derived tumor, but the positivity to CD68 is due to the accumulation of lysosomes that characterizes all neoplasms consisting, in fact, of granular cells." (PMID 34449582, 2021). "We observed significant negative correlations between CD68+ macrophage infiltrations in the tumor tissue and the concentrations of the cytokines eotaxin, IFN-γ, IL-1β, IL-2, IL-10, IL-13, IL-16, VEGF and factor score of component 2 (“Inflammatory Cluster”) in the CSF." (PMID 34654395, 2021).
tumor (continued). "Interestingly, a high number of CD3 + TILs is associated with high CD68 and CD163 expression in tumor nests, but not in the stroma, implicating a distinct colonization mechanism for lymphocytes and macrophages in various tumor compartments." (PMID 34200100, 2021). "In corroboration with this result, direct visualization of tumor-infiltrating immune cells confirmed that tNLR correlated directly with both neutrophil (CD15+ cells, Spearman’s rho 0.398, p = 0.0198) and macrophage (CD68+ cells, Spearman’s rho 0.515, p = 0.0018) cell counts." (PMID 33580206, 2021). "However, after adjusting for hrHPV status, myeloid marker densities in the IT Tumor compartment were no longer significantly associated with survival (CD14 p = 0.65, CD68 p = 0.96, CD163 p = 0.53)." (PMID 34194435, 2021). "Recent reports demonstrated HL patients with the highest M2 TAM count, measured using CD163 or CD68/CD163 as M2 polarization markers, had a significantly reduced disease-free survival (DFS), PFS and OS, further confirming M2 TAM could support tumor progression and immune escape." (PMID 34298810, 2021). "The score for CD68(+) cells in tumor stroma was significantly higher than that in tumor nest and non-epithelium areas of inflammation tissues, suggesting that there was more macrophage infiltration in tumor stroma than in tumor nests, as well as in non-epithelial areas of inflammation cases." (PMID 34407796, 2021). "In the framework made up of cells and stromal tissues surrounding the tumours, the macrophages seem to play a not negligible role: CD68+ macrophages are known to be present in HPV-tumours more than in negative ones; however these cells express PD-L1 mainly in HPV-negative cases." (PMID 33769181, 2021). "Infiltration of CD68+/iNOS− TAMs in the tumor stroma is a negative prognostic factor." (PMID 34445193, 2021). "Three immune cell markers, the chemokine CC motif ligand 2 (CCL2), the pan macrophage marker CD68, and the M2 macrophage marker CD163, were examined using immunohistochemistry to determine their predictive value for chemotherapy responses in different nodal stage and tumor stage subgroups." (PMID 33467469, 2021). "The expression of CD11c and CD68 is similar to lung resident alveolar macrophages but they lack the characteristic CD206 expression, and their accumulation at the tumour edge (interface domain) and some expression of pS6 suggests these might be reactive M1 polarised macrophages." (PMID 34625563, 2021). "To study whether the association of chemotherapy with the prognosis was independent from the immune markers in the different nodal stage and tumor stage patient groups, we performed multivariate Cox’s regression analyses (adjusted for the immune markers CCL2, CD68, and CD163)." (PMID 33467469, 2021). "Multivariable analysis using Cox proportional hazard models indicated that the associations of CD68 + CLS-B with DFS and OS were not altered after adjustment for clinicopathologic factors, including tumour and nodal stage, grade, ER/PgR status and treatment (surgery, chemotherapy, hormone therapy)." (PMID 34294716, 2021). "However, PDL1[T] expression was not correlated with CD8+ T cell/CD68+ M densities in the tumor center and invasion front of MSI or MSS GC." (PMID 33613757, 2021). "As recent studies indicated that infiltrated macrophages could affect the tumor progression, we then performed the immunofluorescence staining of 20 human NSCLC samples with antibodies to ERα and macrophage markers (CD68 and CD163) to examine their relationship in the microenvironment." (PMID 32356397, 2020). "In this study, a quantitative evaluation of macrophages infiltrating CHS tissues, using CD68 as a macrophage marker and CD163 as a marker of alternatively activated M2 macrophages was conducted and the results were compared with the intra-tumor microvessel density (iMVD)." (PMID 32344648, 2020).
tumor (continued). "We detected decreased CD68+ macrophages in both the liver and spleen in VCR/BLZ945 combination‐treated mice when compared with the PBS group or VCR single‐treated mice, indicating that VCR/BLZ945 treatment significantly reduced the abundance of macrophages in tumour‐bearing mice." (PMID 33037771, 2020). "Several immune cell populations; CD68+ macrophages, NKp46+ NKT cells, CD56+NKp46+ NKT cells and CD123+CD15+ granulocytes, had significantly higher infiltration levels in I-type tumors compared to PB-type tumors, both in the tumor and in the stromal compartments." (PMID 33013928, 2020). "Consequently, the F2P Score was established based on the combination of six genomic variables (ESR1, PGR, CD68, BAG1, BCL2, and GSTM1) and two clinicopathological variables (age and categorical tumor size) with the shrinkage factors of 0.314 and 0.888, respectively." (PMID 33042787, 2020). "No cases had significant exclusion of CD68+ infiltrate from tumour epithelium." (PMID 32249277, 2020). "Previous reports have similarly reported that the presence of CD68+ cells could be a negative or a positive prognostic marker across tumours of the same subtype." (PMID 32843682, 2020). "In this study, we described the immune landscape of the OSA tumor microenvironment, along with its heterogeneity, and uncovered the abundant and predominant infiltration of relevant immune cell subtypes (CD4+ Th1 cells and CD68+ macrophages) in the microenvironment." (PMID 32850346, 2020). "In addition, the qRT-PCR revealed overexpression of CD68 in FOXO1(+) tumor tissues, suggesting that tumor-derived FOXO1 could promote macrophage infiltration in vivo." (PMID 33052231, 2020). "Therefore, CD4, CD8, Foxp3, GrB, IL10, and CD68 immune cell markers were studied in order to explore if differences around EBV-infected CG cells and EBV+ tumor cells derived from GC cells could be involved in the malignant transformation." (PMID 31963774, 2020). "Although tumor-associated macrophages represent up to 50% of the GBM cell mass, this staining did not exclude the possibility of another RPS27-positive, but GFAP- and CD68-negative cell type present within the tumor." (PMID 32349320, 2020). "It is interesting that ATX, LPAR1, and LPAR5 are higher in the immune-high tumor (Cd14-, Cd68-, Cd164-, and Cd3E-high) group, but LPAR2.3 are higher in the immune-low group, suggesting the complex regulatory roles of the ATX–LPA axis in the tumor–immune system interaction." (PMID 31658655, 2019). "Interestingly, the expression of macrophage markers in OPA appears to vary depending on their location within the affected tissue, with cells on the periphery of tumor foci being CD68 positive and cells within the tumor being CD163 positive and CD68 negative." (PMID 31434729, 2019). "The relationship between CD68+, not CD3+, was associated with higher tumor stage." (PMID 31905599, 2019). "In summary, TAMs may play an important role in promoting tumor growth, invasion and metastasis in TME of DLBCL, and CD163, as considered to be a marker relatively specific to M2 TAMs may serve as a better predictor than the pan-macrophage marker, CD68." (PMID 31694577, 2019). "Interestingly, further analyses found that MCTC ratio was significantly associated with the expression of CD163 (r = 0.526, P < 0.001), but not with CD68 at tumor invasive front (r = 0.128, P = 0.256)." (PMID 30927925, 2019). "The expression of CD68 was significantly associated with the clinical stage, perineural invasion, and distant metastasis of SACC (P < 0.05), whereas not with age, gender, tumor site, and tumor histotype (P > 0.05)." (PMID 31024838, 2019). "Moreover, PD-L1+ tumor cells (PDL1+CD68−) were weakly or not correlated with these three T cell subsets." (PMID 31783783, 2019). "Interestingly, nonimmune cells of the TME, including ECs did not efficiently internalize pHLIP when compared with CD68+ macrophages within the tumor." (PMID 31710308, 2019).